ATF3 (activating transcription factor 3)
Diseases named in the same sentence as ATF3 in open-access papers (continued):
Sharing a sentence is not in itself a finding about the gene and the disease.
cancer (continued). "These 11 specific ATF3 target genes had very noticeable differences between cancer and adjacent normal tissues." (PMID 28402947, 2017). "TOLE can inhibit cell growth in cancer cells through cyclooxygenase-independent pathways including inhibition of ErbB2 expression, activation or ATF3, or induction of NSAID-activated gene-1 (NAG-1) and EGR1." (PMID 29228577, 2017). "Among these genes, activating transcription factor 3 (ATF3) plays a central role in the key events triggered by Onconase in treated cancer cells that finally lead to apoptosis." (PMID 28035074, 2017). "Although the function of ATF3 extends to other physiological responses, ATF3 appears to play a role mainly in inflammation and cancer." (PMID 28860159, 2017). "ATF3 is well-studied in a wide diversity of human cell types including hepatocytes, activated T-cells, skeletal muscle cells, macrophages, as well as cancer cell lines and immortalized cell lines." (PMID 28790348, 2017). "ATF3 is a transcription factor whose role in cancer is clearly cellular-context dependent, but it seems essential for the maintenance of host defense mechanisms." (PMID 28035074, 2017). "Accumulating evidence suggests that ATF3 plays a pivotal role in cancer development by regulating the balance between survival and cell death." (PMID 28860159, 2017). "The most striking studies supported an oncogenic role of ATF3 based on correlative evidence of ATF3 overexpression in human cancer tissue." (PMID 28402947, 2017). "The ATF3 expression is elevated in many human cancers, including breast, prostate, and Hodgkin lymphoma cancers." (PMID 28402947, 2017). "In terms of the importance of apoptosis to cancer prevention, ATF3 can be thought of as an important molecular target in the induction of apoptosis." (PMID 27043582, 2016). "We confirm that, when faced with different cell types and driving factors, ATF3 plays different roles in the developmental process of cancer." (PMID 25872784, 2015). "It has been reported that activating transcription factor 3 (ATF3) is expressed in elevated levels in multiple malignant tumors." (PMID 25872784, 2015). "ATF3 is somewhat enigmatic since it functions as a dualistic transcription factor with both anti- and pro-tumorigenic effects, depending on the cancer subtype." (PMID 26418018, 2015). "Under optimal conditions, comparing the changes in gene expression observed in three different xenografted cancers, only one gene, ATF3, was up-regulated in common." (PMID 26647838, 2015). "We focused on Atf3 as an IEG in which there is great interest because of its association with inflammation, cancer and cardiac dysfunction." (PMID 24811474, 2014). "In cancer development, ATF3 exerts pro-or anti-apoptotic activities dependent on cell or tissue context." (PMID 25338635, 2014). "Intriguingly, we found that effect of ATF3 on cell invasion was greater than that on cell growth, which prompted us to focus our studies on ATF3 role in cancer invasion." (PMID 25149542, 2014). "For the incidence and development of cancer, the roles of ATF3 in cancer progression and anti-cancer therapeutics are complex." (PMID 25494848, 2014). "Anti-cancer activity of MRBE is associated with ROS-dependent cyclin D1 proteasomal degradation and ROS/ GSK3β-dependent ATF3 expression." (PMID 24962785, 2014). "Another member of the CREB/ATF family that binds CRE sites, ATF3, is a repressor and is overexpressed in many cancer cells." (PMID 24895212, 2014). "It was shown that ATF3, a Wnt/β-catenin target gene in cancer cell lines, can either transcriptionally repress Pdx1 expression or physically interact with PDX1 to block PDX1 mediated transactivation in a murine β-cell line." (PMID 23741453, 2013). "Many publications indicated that ATF-3 is involved in several physiologic and pathologic processes including homeostasis, wound healing, cell adhesion, cancer-cell invasion, apoptosis, and other signal transduction pathways." (PMID 24222778, 2013).
cancer (continued). "ATF3 is another stress-inducible gene upregulated in many cancers and also in SMCs within injured mouse femoral arteries, to promote SMC migration and ECM synthesis." (PMID 23874238, 2013). "ATF3 has been demonstrated to play a role in apoptosis and proliferation, two cellular processes critical for cancer progression." (PMID 22461839, 2012). "Among them, we focused on ATF3 for the following reasons: First, ATF3 was reported to play a role in both survival and proliferation of cancer cells." (PMID 21414204, 2011). "Our finding that ATF3 has opposing effects on pro-apoptotic genes suggests that care must be taken to either enhance or block the function of ATF3 in a novel approach to cancer therapy." (PMID 22046379, 2011). "It has also been pointed out that the ATF3 gene has a potential dichotomous role in cancer development: it has pro-apoptotic functions, like a tumor suppressor, but at the same time induces cell proliferation, like an oncogene." (PMID 21414204, 2011). "It has previously been shown by both our group and others that nelfinavir induces the endoplasmic reticulum stress response in solid human cancer cells, resulting in upregulation of BiP, phosphorylation of eIF2, upregulation of ATF3, and autophagy." (PMID 20105315, 2010). "Typically, ipsilateral cancer DRG sections displayed seven times more ATF3-positive neurons than their corresponding contralateral part or the sham group." (PMID 21048940, 2010). "We now have confirmed that blocking Hsp90 does indeed induce ATF3 in various cancer derived cell lines, including colon (HT29, HCT116), gastric (TMK1), and pancreatic (L3.6pl) cancer derived cells." (PMID 21129190, 2010). "The HDAC inhibitor M344 induced ATF3 expression at the protein and mRNA level in a panel of human derived cancer cell lines as determined by Western blot and quantitative RT-PCR analyses." (PMID 20828393, 2010). "Human HCT116 cancer cells were stably transfected with an ATF3-shRNA or a luciferase-shRNA expression plasmid and alterations in cell motility were assessed in migration assays." (PMID 21129190, 2010). "This is the first study to characterize this regulation in multiple cancer cell lines as well as address the mechanism of HDAC inhibition induced ATF3 expression." (PMID 20828393, 2010). "ATF3 has been shown to play a role in apoptosis and proliferation, two cellular processes critical for cancer progression." (PMID 20828393, 2010). "Divergence in function of ATF3 between a pro-and anti-apoptotic factor in cancer models is dependent on both cellular model and state of malignancy." (PMID 20828393, 2010). "Although the physiologic functions of ATF3 are not well understood, there is some evidence that ATF3 functions as a pro-apoptotic gene in cancer cells." (PMID 21034493, 2010). "Regulation of ATF3 was determined in cancer cells using signaling inhibitors and a heat-shock protein-90 (Hsp90) antagonist." (PMID 21129190, 2010). "In this study, we identified ATF3 as a novel consistently inducible target of HDAC inhibitor treatment in a panel of human derived cancer cell lines both at the protein and mRNA level." (PMID 20828393, 2010). "ATF-3 inhibits cancer cell proliferation and invasion, and its induction correlates with cellular damage." (PMID 17764562, 2007). "While prior studies have emphasized that DSF/Cu induces ferroptosis and cuproptosis in the treatment or progression of cancers 20, 21, our work reveals a novel ATF3-mediated pathway through which DSF/Cu induces mitochondrial damage and subsequent apoptosis, ultimately suppressing HCC progression." (PMID 41438581, 2026).
cancer (continued). "For instance, the transcription factor ATF3 has been demonstrated to function as both a transcriptional activator and a repressor, it can either promote or suppress apoptosis and proliferation, two critical processes for cancer progression." (PMID 39680504, 2025). "Furthermore, ATF3 and ERK pathway-associated and glycolysis-related proteins were up-regulated in CCDC86 highly expressed cancer tissues compared with adjacent normal tissues with low CCDC86 expression." (PMID 40837407, 2025). "Investigating the influence of MES on ferroptosis-related genes, especially ATF3, HMOX1 and CDKN1A, may provide valuable insights into the molecular mechanisms underlying its action and offer potential therapeutic strategies for cancer treatment." (PMID 39857803, 2025). "Exploring ATF3 inhibitors and mitochondrial protection strategies could lead to safer and more effective future cancer treatments." (PMID 40880646, 2025). "Moreover, KU (20 mg/kg i.p. injections for 16 days) applied to mice with CT26 metastatic colon cancer cells reduced the number of metastatic nodules in livers, elevating ATF3 and cancer cell apoptosis levels." (PMID 39457512, 2024). "Notably, our study highlights that the ATF3-CBS signaling axis enhances ferroptosis-based CRC cancer therapy." (PMID 38490069, 2024). "Interestingly, inhibiting SCD1 to block MUFA production was also shown to induce ER stress, in which ATF3 plays a critical role in mediating the downstream cellular responses in both cancer and other health conditions." (PMID 38586033, 2024). "However, further investigation is required regarding the involvement of the activating transcription factor 3 (ATF3)-mediated Tat-interactive protein 60 (Tip60)/Foxo3a pathway in cancer cell apoptosis." (PMID 35283423, 2022). "ATF3 makes the WT macrophages more cancer friendly by dampening their cytotoxicity." (PMID 34298975, 2021). "Several studies found that ATF3 is downregulated in many human cancers." (PMID 34681694, 2021). "Therefore, ATF3 is involved in the regulation of tumorigenesis, and its potential function depends on the cancer types and cell-specific context." (PMID 34728784, 2021). "However, ATF3 plays different roles in cancer development depending on the cancer cell type and environment." (PMID 33407456, 2021). "Initially, CTX enhanced cancer cell retention in both WT and Atf3 KO lungs." (PMID 34298975, 2021). "Although most studies indicated ATF3 could inhibit cancer cell growth via increasing apoptosis in multiple cancers, other groups found that ATF3 may increase cancer cell proliferation." (PMID 33390173, 2021). "That is, CTX increased the abundance of cancer cells at the late-stage only in the wild type (WT) mice but not the knockout (KO) mice deficient in Atf3." (PMID 34638621, 2021). "However, the effect at the late-stage is dependent on a stress-inducible gene Atf3 in the non-cancer cells in the host (the host-Atf3)." (PMID 34638621, 2021). "Thus, as a stress-inducible gene, Atf3 in the host cells links chemotherapy (a stressor) to altered transcriptional programs and makes the host environment more cancer friendly." (PMID 34298975, 2021). "Therefore, macrophage has a dichotomous role, either pro-cancer or anti-cancer, depending on its status of Atf3." (PMID 34638621, 2021). "Some studies have indicated that ATF3 expression is downregulated in human cancers, such as in colon cancer, liver cancer, multiple myeloma, neuroblastoma, prostate cancer, malignant glioma, and non-small cell lung carcinoma, compared to its level in normal tissues." (PMID 33816467, 2021). "However, the Atf3 KO lung is less conducive for cancer cells to extravasate or survive, leading to an overall lower lung colonization in the Atf3 KO than WT lungs." (PMID 34298975, 2021). "Since some cancer stem cells acquired EMT potentials, the connection between ATF3 and EMT may indicate an important perspective of ATF3 in the functional specialization of the cancer stem cells." (PMID 35052581, 2021).
cancer (continued). "Meanwhile, ATF3 is also important for the colonization of the cancer cells in the metastatic sites in the lung through prompting expression of chemokine C-C motif ligand 2 (CCL2) that recruits inflammatory monocytes and VEGFR1+ macrophages that favor metastasis and immunosuppression." (PMID 35052581, 2021). "These ATF3-induced tumors were also found to have reduced expression of Mir145 and Mir143, leading to upregulation of the transcription factors Klf4 and Sox2 and the cancer stem cell-related gene Kras, respectively." (PMID 33652981, 2021). "Activating transcription factor 3 (ATF3) plays a major role in cancer development." (PMID 34631548, 2021). "Taken together, these results support a novel relationship between NR5A1 and ATF3 and this relationship may have an impact in organ differentiation and cancer development." (PMID 32093223, 2020). "This study further found that the combination of ATF3-inducing agents (e.g., trifluridine or vorinostat) with doxorubicin may be utilized as a novel therapeutic application for this type of cancer." (PMID 32922364, 2020). "Furthermore, expression of N-myc downstream regulated gene 1 (NDRG1), a gene that is regulated by hypoxia and cellular proliferation signaling, and can act to both promote and suppress some cancers, has been shown to counteract the function of ATF3." (PMID 33302475, 2020). "Given that emerging evidence links ferroptosis to various pathological conditions (e.g., cancer and neural injury) often involving induction or aberrant expression of ATF3, our finding suggests that ATF3 may regulate these events by promoting ferroptosis." (PMID 31273299, 2020). "Since both NR5A1 and ATF3 can regulate and cooperate with several transcription factors, we hypothesized that NR5A1 may interact with ATF3 and plays a functional role in cancer development." (PMID 32093223, 2020). "Although ATF3 may regulate cancer progression and metastasis in a context-dependent manner, we have shown that Atf3−/− mice are prone to spontaneous tumorigenesis and Atf3-deficient cells are genetically unstable." (PMID 31796886, 2020). "In addition, these results suggest the role of ATF3 is heterogeneous in different cancer cell content." (PMID 31410216, 2019). "Therefore, the identification of ATF3 targets represents an important means of accurately understanding how this protein contributes to cancer." (PMID 31410216, 2019). "ATF3 was found to mediate anticancer activity in several malignant tumors." (PMID 30723510, 2019). "Moreover, ATF3 has been determined to bind to the regulatory regions of Gelsolin, resulting in the up-regulation of Gelsolin to prevent cancer cell metastasis." (PMID 29515366, 2018). "On the other hand, the rescue experiments confirmed that CYR61 knockdown could remarkably decrease the anti-cancer function of ATF3 overexpression." (PMID 30376856, 2018). "In this study, we sought to understand the molecular mechanism and biological role of Wnt/β-catenin dependent ATF3 gene expression better by using HCT116 human cancer cells that were genetically engineered to possess a wild-type or mutant allele of the β-catenin gene loci." (PMID 29966001, 2018). "Substantial evidence shows that ATF3 may play an important role as a host defense by balancing the proliferative and apoptotic signals that are related with the progression of cancer." (PMID 28402947, 2017). "However, there is some evidence indicating the contrary, suggesting that ATF3 inhibits cancer formation." (PMID 25872784, 2015). "There is evidence in the literature that ATF3 may often promote the invasion and metastasis of cancer cell lines in vitro and in vivo." (PMID 25872784, 2015).
cancer (continued). "ATF4, ATF3, and CHOP were downregulated in PKCδ-deficient cancer cells." (PMID 26188905, 2015). "Recently, more and more evidence indicates that ATF3 may play a critical role in the progression of cancer." (PMID 25149542, 2014). "ATF3 was a transcription factor involved in the progression of certain cancers." (PMID 25149542, 2014). "We then investigated the mechanisms by which ATF3 modulated cancer cell invasion and metastasis." (PMID 25149542, 2014). "Abnormal expression of ATF3 may mediate multiple aspects of cancer biology by repressing the transcription of certain downstream molecules including Cyclin D1, Id1 and IRS2." (PMID 25149542, 2014). "Interestingly, ATF3 has been demonstrated to play differing roles in cancer development depending on the cell type and context." (PMID 25149542, 2014). "Moreover, another report suggested that ATF-3 has a potential dichotomous role in cancer development, since ATF3 was found to enhance apoptosis in untransformed cells but prevented apoptosis in malignant cells." (PMID 24222778, 2013). "Furthermore, ATF3 has been reported to affect cell death and cell cycle progression, 2 processes that regulate the growth of cancer cells." (PMID 23028726, 2012). "In cancer cells, ATF3 has also been identified as an inhibitor of Ras-stimulated tumorigenesis." (PMID 22768301, 2012). "Given the emerging role of HDAC inhibitors as anti-cancer agents, we evaluated whether ATF3 also regulates their activities." (PMID 20828393, 2010). "To further validate these results, we investigated whether blocking Hsp90 also leads to ATF3 up-regulation in other human cancer cell types." (PMID 21129190, 2010). "However, inhibitors of PERK signaling, which ATF3 helps mediate, do have anti-cancer activities and could be evaluated for ATF3 modulation." (PMID 41198649, 2025). "Further, the FLNA editing state influenced genes associated with proliferation, cancer, and stress response, with some being upregulated in FLNAR (e.g., Naca, Myof, Smoc2, and Hprt) and others being upregulated in FLNAQ ECs, like the AP-1 transcription factor complex (Atf3, Fos, and Jun)." (PMID 40471139, 2025). "In addition, deletion of Atf3 in acinar cells altered expression of pathways involved in cancer progression through direct and indirect mechanisms, targeting positive and negative regulators of KRAS signaling that lead to decreased signaling through the MAPK pathway." (PMID 41198649, 2025). "Moreover, GSEA revealed that AREG, ATF3, ZFP36, and DUSP1 may regulate OSA via inflammation and contribute to OSA-related cancer risk." (PMID 35372438, 2022). "This implies that the physiological function of ATF3 may vary among the different types of cancer." (PMID 35283423, 2022). "Therefore, understanding the epigenetic regulation of ATF3 by PXR in tumors, such as deletion, mutation, or posttranslational modifications, may help to determine more effective therapeutic methods for cancer patients." (PMID 35372071, 2022). "Besides, GEPIA web tools also showed that ATF3 was significantly expressed with poor prognosis in many cancers, further suggesting that ATF3 might play an anti-oncogenic role in various types of human cancer." (PMID 33816467, 2021). "Other studies indicated that ATF3 could also increase progression in certain cancers." (PMID 33390173, 2021). "Multiple mechanisms may contribute to the reduction of Atf3 in the late stages of cancer." (PMID 33172040, 2020). "Once the signaling pathways of ATF3 activation become elucidated, the activators of these pathways could be alternative strategies for targeting Noxa to efficiently induce cell death for cancer treatment." (PMID 29352505, 2018).